PAPOLB (poly(A) polymerase beta)
Synonyms: PAPT; TPAP
Tractability: PROTAC: ubiquitination databases record sites on it.
Gene: Protein-coding gene on chromosome 7 (4,857,738 to 4,862,030, reverse strand). Ensembl gene ENSG00000218823.
Subcellular location: Cytoplasm; Nucleus
Subcellular location (Human Protein Atlas): Nucleoplasm
Gene Ontology:
Molecular function: poly(A) RNA polymerase activity; nucleotidyltransferase activity; RNA binding
Biological process: RNA 3'-end processing
Cellular component: cytoplasm; endoplasmic reticulum; nucleus
Genetic constraint (gnomAD): Loss-of-function variants: 20 observed, 27.55 expected, observed/expected ratio (o/e) 0.73, 90% interval 0.51 to 1.05. The synonymous counts are far from expectation, so gnomAD's model fits this gene poorly and the ratio says little. Missense variants: 815 observed, 793.8 expected, observed/expected ratio (o/e) 1.03, 90% interval 0.97 to 1.09. Synonymous variants: 357 observed, 292.88 expected, observed/expected ratio (o/e) 1.22, 90% interval 1.12 to 1.33.
Homologues: Orthologues: chimpanzee PAPOLB (98% identical), dog PAPOLB (86% identical), rat Papolb (86% identical), mouse Papolb (85% identical), guinea pig PAPOLB (65% identical), Drosophila melanogaster hrg (50% identical), Caenorhabditis elegans pap-1 (40% identical), Caenorhabditis elegans pap-3 (39% identical), Caenorhabditis elegans pap-2 (38% identical). Paralogues in human: PAPOLA (84% identical), PAPOLG (60% identical).